BCL6 (BCL6 transcription repressor)
Diseases named in the same sentence as BCL6 in open-access papers (continued):
Sharing a sentence is not in itself a finding about the gene and the disease.
Arthritis (4 papers, 2013 to 2022). Inflammation of a joint. "Because BCL6 plays a dominant role in T cell and B cell responses, the effect of FX1 treatment on Lyme arthritis severity was evaluated in B6 Rag1-/- mice to determine the contribution of T cells and B cells to IFNβ production and arthritis." (PMID 35324997, 2022). "FX1-treated B6 Rag1-/- mice displayed more severe Lyme arthritis than vehicle-treated control B6 Rag1-/- mice indicating that BCL6 expression in non-lymphocytes, such as myeloid cells, is critical for the increased arthritis severity observed upon FX1 treatment." (PMID 35324997, 2022). "Our study shows that alcohol alters the activity of TFH cells by down-regulating key activation nodes such as Bcl6, PD-1 and IL-21, thereby preventing the formation of functional TFH:B cell conjugates and ultimately leading to a decline in autoantibody production and lower incidence of arthritis." (PMID 32332730, 2020).
bladder cancer (4 papers, 2007 to 2025). "Considering the expression of Bcl-6 only in tumors, we can suggest that the expression of this transcription factor is associated with a good prognosis in bladder cancer." (PMID 27237631, 2016). "The results demonstrate that FLLL31 inhibits malignant bladder cancer behaviors by inducing apoptosis via the FOXO4/BCL6 axis." (PMID 41438489, 2025). "Expression of T-bet, GATA-3 and Bcl-6 genes was assessed using RT-qPCR in 65 bladder cancers from patients: 32 being diagnosed as low- and medium-grade, 31 as high-grade, 25 as muscle invasive stage and 39 as non-muscle invasive stage." (PMID 27237631, 2016). "Next, we analyzed T-bet, GATA-3, and Bcl-6 levels in relation to OS of patients with bladder cancer." (PMID 27237631, 2016). "Real-time PCR analysis showed that Bcl-6 gene expression was higher in non-invasive bladder cancer tissue (Tis, Ta, and T1) than in invasive bladder tumors (T2–T4) (p = 0.0003)." (PMID 27237631, 2016). "The aim of this study was to investigate the clinical significance of three immune cell-related transcription factors, T-bet, GATA-3 and Bcl-6 in bladder cancer in Tunisian patients." (PMID 27237631, 2016). "In contrast, reductions in Bcl-6 and GATA-3 expression correlated with invasive and high-grade of bladder cancer and were associated with a decrease in disease-free survival." (PMID 27237631, 2016). "We next assessed whether Bcl-6 gene expression in bladder cancer was correlated to the clinic-pathological features of patients." (PMID 27237631, 2016). "In contrast, the expression of GATA-3 and Bcl-6 in non-invasive carcinoma (p = 0.008 and p = 0.0003) and in patients with low- and medium-grade cancers (p = 0.001 and p < 0.0001) is significantly higher than in invasive bladder tumors and in patients with high-grade bladder carcinoma, respectively." (PMID 27237631, 2016). "The aim of this study is to assess the prognostic value of three genes in tumors from bladder cancer patients in Tunisia: T-bet, GATA-3 and Bcl-6." (PMID 27237631, 2016).
breast tumors (4 papers, 2013 to 2018). "In line with previous works, we observed Bcl6+ B lymphocytes and Tfh cells within GC which argue for functional ectopic centers in breast tumors." (PMID 25884667, 2015). "Interestingly, we observed that miR-127 and its target, BCL-6,are inversely correlated and that their expression profiles are opposite in breast tumors and matched adjacent tissues." (PMID 24282530, 2013). "Additionally, we found an inverse correlation of expression between BCL6 and miR-127 in primary breast tumors versus adjacent normal tissues." (PMID 24282530, 2013).
diabetes (4 papers, 2014 to 2025). "Overall, this study identified several ways in which BCL6-expressing T cells redirected insulin-binding B cells towards pro-pathogenic fates, which were associated with diabetes development." (PMID 40909612, 2025). "Here, we show that VH125SD.NOD mice with T cell loss of BCL6 still produce peripheral anti-insulin B cells yet are protected against diabetes (relative to Bcl6-sufficient controls)." (PMID 40909612, 2025). "Despite the presence of anti-insulin B cell populations in peripheral organs, T cell loss of Bcl6 in VH125SDBcl6ΔCD4 mice led to nearly complete diabetes protection relative to control VH125SD.NOD mice." (PMID 40909612, 2025). "Here, we show that despite VH125SD BCR transgene-forced expansion of anti-insulin B cells, T cell loss of Bcl6 led to nearly complete prevention of diabetes in VH125SD mice." (PMID 40909612, 2025). "Thus, T cell loss of Bcl6 prevents diabetes in VH125SD.NOD mice despite the expanded pool of anti-insulin B cells that reach the periphery." (PMID 40909612, 2025). "Previous studies have demonstrated that the FOXO/BCL6/cyclin D2 pathway linked to β-cell proliferation and may therefore be considered to be associated with diabetes." (PMID 26308950, 2015). "To address whether CD4-targeted Bcl6 elimination prevents diabetes even when such a “T1D-poised” B cell repertoire has formed, we generated VH125SD.Bcl6fl/fl.NOD (termed VH125SD.NOD hereafter) and VH125SD Bcl6fl/fl.CreCD4.NOD (termed VH125SDBcl6ΔCD4) mice." (PMID 40909612, 2025). "T cell expression of BCL6, a key transcriptional repressor in the germinal center response, is essential for spontaneous diabetes in non-obese diabetic (NOD) mice." (PMID 40909612, 2025).
dyslipidemia (4 papers, 2016 to 2023). "Sex differences caused by Bcl6 in bacterial infections and dyslipidemia suggested that Bcl6 is important in the evolution of immune differences between males and females." (PMID 36497010, 2022).
Insulin resistance (4 papers, 2022 to 2025). Increased resistance towards insulin, that is, diminished effectiveness of insulin in reducing blood glucose levels. "Further, forced expression of BCL6 lowered blood glucose levels as well as HFD-induced insulin resistance." (PMID 37681868, 2023). "More importantly, BCL6 overexpression substantially curtailed HFD-induced insulin resistance and lowered the serum glucose profile." (PMID 37681868, 2023). "Conversely, BCL6-CKO mice demonstrated insulin resistance and had poorer glucose tolerance." (PMID 35436984, 2022). "This study found that the increased hepatic BCL6 expression sufficiently inhibits CD36 gene expression and subsequent hepatic lipid accumulation, while also exerting a positive effect on insulin resistance in HFD-fed mice." (PMID 35436984, 2022). "It should be noted that BCL6 upregulation in hepatocytes was sufficient in inhibiting CD36 gene expression and lipid accumulation in the liver, resulting in an overall improvement in HFD mice insulin resistance." (PMID 35436984, 2022).
liver fibrosis (4 papers, 2014 to 2022). "In this study, we analysed the role of Bcl6 in NASH progression-associated pathological changes, such as hepatic lipid accumulation, liver fibrosis, and hepatocarcinogenesis." (PMID 32546802, 2020). "The short-term CDAHFD feeding resulted in the induction of NASH-like pathologies, such as liver injury, hepatic lipid accumulation, and liver fibrosis in WT mice, which were suppressed in Bcl6-LKO mice." (PMID 32546802, 2020). "The Bcl6-LKO mice exhibited suppressed accumulation of fatty acids and suppressed level of liver injury and liver fibrosis, which were induced by CDAHFD feeding." (PMID 32546802, 2020).
lung adenocarcinoma (4 papers, 2015 to 2022). A carcinoma that arises from the lung and is characterized by the presence of malignant glandular epithelial cells. "Moreover, BCL6 was highly expressed in human KRAS-mutant lung adenocarcinomas and was associated with poor patient survival." (PMID 36377663, 2022). "As expected, this analysis indicated that the highest BCL6 expression was found in DLBCL samples, but also that relatively high BCL6 levels were seen in both lung adenocarcinoma and squamous cell carcinoma." (PMID 32234966, 2020).
myocarditis (4 papers, 2019 to 2022). Myocarditis is a condition that is characterized by inflammation of the heart muscle (myocardium). "Over 80% of Bcl6−/− mice developed myocarditis, and over 70% of mice suffered from pulmonary vasculitis, with high levels of IL-4, −5, and −13." (PMID 35436984, 2022). "Over 80% of Bcl6-/- mice exhibit myocarditis and over 70% have pulmonary vasculitis with elevated levels of IL-4,–5, and −13, cytokines known to directly impact liver metabolism." (PMID 30983568, 2019).
plasmacytoma (4 papers, 2006 to 2025). Plasmacytoma is a localized mass of neoplastic monoclonal plasma cells that represents approximately 5% of all plasma cell neoplasms. "The tumor cells were lambda light chain restricted and positive for CD45, weakly positive for CD79a and negative for CD20, CD30, CD10, CD5, BCl-2, Bcl-6, Pax5 and S100, and consistent with anaplastic plasmacytoma." (PMID 19495405, 2009).
Sepsis (4 papers, 2022 to 2024). Sepsis is defined as life-threatening organ dysfunction caused by a dysregulated host response to infection. "Intriguingly, branching analysis indicated that BCL6, an E. coli sepsis signature gene, was associated with fate decision (Padj = 2.3e-24)." (PMID 37919720, 2023). "For sepsis, we found that PLCG2 was upregulated in immune cells during sepsis compared to healthy individuals, BCL6 was upregulated in Pre-B cells (CD34−) during sepsis, and IGF2BP2 was upregulated in GMP cells." (PMID 38167131, 2024). "While BCL6 is not directly implicated in inflammation and sepsis, it plays a role in modulating immune responses and can influence the balance between pro-inflammatory and anti-inflammatory signaling pathways." (PMID 38167131, 2024). "In addition, our study of lincRNA located near differentially deregulated genes highlights the role of BCL6, known as an inhibitor of macrophage-mediated inflammatory responses and involved in sepsis development as demonstrated in a recent publication in a mouse model." (PMID 35055007, 2022). "We identified significant upregulation of NTSR1, BCL6, ZDHHC19, MGLL, and ALPK1 in sepsis compared to healthy individuals, while VAV2 and SATB1 were significantly downregulated in sepsis." (PMID 38167131, 2024). "The observed significant upregulation of NTSR1, BCL6, ZDHHC19, MGLL, and ALPK1 in sepsis compared to healthy individuals, along with the notable downregulation of VAV2 and SATB1 in sepsis, provides a comprehensive picture of the altered gene expression landscape during sepsis." (PMID 38167131, 2024). "Additionally, bulk RNA analysis revealed significant increases in NTSR1, BCL6, ZDHHC19, MGLL, and ALPK1 in sepsis, and significant decreases in VAV2 and SATB1 in sepsis; FCHO1 showed a significant decrease in sepsis patients who did not survive compared to those who survived at 28 days." (PMID 38167131, 2024).
extranodal NK/T-cell lymphoma nasal type (3 papers, 2012 to 2023). "As mentioned, the BCL6 mRNA was also up-regulated in NK/T-cell lymphomas." (PMID 22870299, 2012). "For example, in nasal natural killer/T-cell lymphoma (NKTCL), which is commonly linked to Epstein–Barr virus (EBV), miR-142-3p is downregulated and IFNγ production is inhibited, thereby promoting lymphoma transformation with increased oncogenic BCL6 and IL1A cytokine expression." (PMID 38201290, 2023).
heart failure (3 papers, 2024 to 2025). Inability of the heart to pump blood at an adequate rate to meet tissue metabolic requirements. "After intersecting the results of the three algorithms, we obtained four down-regulated key aging genes in heart failure, namely BCL6, EIF4EBP1, MEIS2, and SMARCA2." (PMID 38686376, 2024). "Thus, under pathological conditions, aberrantly downregulated DDX17 expression can lead to reduced BCL6 transcriptional repression, resulting in cardiomyocyte injury and the development of heart failure." (PMID 38782919, 2024). "When DDX17 expression is reduced, transcriptional repression of BCL6 is attenuated, leading to increased DRP1 expression and mitochondrial fission, which in turn leads to impaired mitochondrial homeostasis and heart failure." (PMID 38782919, 2024).
high grade B-cell lymphoma (3 papers, 2021 to 2024). A term that refers to high grade B-cell lymphoma, not otherwise specified or high grade B-cell lymphoma with MYC and BCL2 and/or BCL6 rearrangements. "Differentiating DLBCL NOS from other LBCL types, particularly from DLBCL/high-grade B cell lymphomas (HGBL) with MYC/BCL2 rearrangements (double hit), typically involves morphological assessment, immunophenotyping, and fluorescence in situ hybridization (FISH) for BCL2, BCL6, and MYC rearrangements." (PMID 38927948, 2024).
invasive breast carcinoma (3 papers, 2013 to 2018). A carcinoma that infiltrates the breast parenchyma.
Kaposi's sarcoma (3 papers, 2014 to 2025). A malignant neoplasm characterized by a vascular proliferation which usually contains blunt endothelial cells. "Statistical analyses identified CD10 negativity, BCL-6 negativity, Epstein–Barr virus positivity, and Kaposi sarcoma-associated herpesvirus positivity as risk factors for poor prognosis." (PMID 24407967, 2014).
liver cancer (3 papers, 2017 to 2024). An epithelial or non-epithelial malignant neoplasm that arises from the liver. "We sacrificed the mice on day 14, and the liver image, liver weight, tumor area as well as the H&E staining all supported that overexpression of Bcl6 promoted liver cancer progression." (PMID 38956432, 2024). "To uncover the mechanism how Bcl6 affects liver cancer progression, we applied single-cell RNA to analyze the expression of tumor cells and infiltrating immune cells." (PMID 38956432, 2024). "Conclusively, these data suggested that liver cancer cells express higher level of BCL6 compared with normal hepatocytes, and the expression of BCL6 in HCC tissue is correlated with poor clinical outcome." (PMID 38956432, 2024). "To confirm the function of BCL6 in liver cancer progression, we overexpressed Bcl6 in Hepa1-6, which is a more mild HCC cell line compared to H22." (PMID 38956432, 2024). "Within the regions prioritised by the combined score, we also identified several extremely highly conserved regions that are recurrently mutated in the LIRI-JP cohort (liver cancer), including non-coding regions of the genes BCL11A, BCL6, and PAX5." (PMID 28056774, 2017). "We also tested the function of BCL6 overexpression on inflammatory gene expression in mouse liver cancer cell line Hep53.4 and human liver cancer cell line Hep3B with qPCR, which both supported that BCL6 overexpression suppressed inflammatory genes expression which promote ESM1 expression." (PMID 38956432, 2024). "Thus, to study the role of BCL6 in liver cancer progression, we used mouse cell lines H22 and Hepa1-6 which were derived from BALB/c and C57 respectively." (PMID 38956432, 2024). "Collectively, in this part we have shown that knockout of Bcl6 increased HCC cancer cell expression of pro-inflammatory genes while decreasing the expression of anti-inflammatory gene expression including ESM1, and ESM1 promotes liver cancer progression." (PMID 38956432, 2024).
metastatic tumors (3 papers, 2021 to 2026). "When comparing the 54 primary and 36 metastatic cervical adenocarcinoma samples in our study, BCL6 and CLTCL1 mutations were found exclusively in metastatic tumors." (PMID 41597409, 2026). "BCL6 was present in 11.1% of metastatic tumors (n = 4), while CLTCL1 alterations appeared in one metastatic sample (2.8%)." (PMID 41597409, 2026). "We did, however, find small LAs in metastatic tumors, which lacked BCL6+ germinal center and could not be defined as mature TLS." (PMID 37768208, 2023).
osteoporosis (3 papers, 2022 to 2025). A condition of reduced bone mass, with decreased cortical thickness and a decrease in the number and size of the trabeculae of cancellous bone (but normal chemical composition), resulting in increased fracture incidence. "Overexpression of Bcl6 inhibits osteoclastogenesis, and Bcl6-deficient mice show increased OC differentiation, leading to severe osteoporosis." (PMID 36362318, 2022). "Differential expression analysis in osteoporosis and sarcopenia datasets revealed that seven biomarkers—BCL6, DDIT4, FOXO1, IRS1, NFKBIA, PGK1, and STAT3—were differentially expressed in the independent osteoporosis dataset GSE84500." (PMID 41282482, 2025). "Specifically, the identification of PTBP1, H2AFZ, BCL6, and TTPAL as the regulators of osteogenic differentiation presents novel therapeutic targets for conditions such as osteoporosis and bone fracture healing." (PMID 39766835, 2024).
periodontitis (3 papers, 2020 to 2025). An acute or chronic inflammatory process that affects the tissues that surround and support the teeth. "Recent studies utilizing single-cell sequencing (scRNA) technology in the periodontal tissues of periodontitis-affected or healthy individuals revealed the differential expression of the BCL6, FOS, and JUN MRs during osteoclastogenesis." (PMID 37834287, 2023). "Taken together, our findings propose a model whereby the overexpression of CTGF in chronic periodontitis tissues induces the suppression of Bcl6, which results in hyper-osteoclast differentiation and subsequent loss of bone mass." (PMID 32210715, 2020). "Finally, we shed light on the Bcl6-osteoclastic gene axis which is recognized as a force of negative regulation of osteoclast differentiation to study the pathway CTGF undertakes in periodontitis." (PMID 32210715, 2020). "In contrast, 8 MRs (ESR1, CEBPB, FOS, BCL6, E2F1, SPI1, STAT3, and ETS1) were consistently expressed at higher levels (U test statistic between 10 and 16) in the periodontitis condition." (PMID 37834287, 2023). "Findings from this study suggest that CTGF promotes the fusion of pre-osteoclasts by downregulating Bcl6 and subsequently increasing the expression of DC-STAMP in periodontitis." (PMID 32210715, 2020).
plasma cell neoplasm (3 papers, 2006 to 2025). A clonal proliferation of immunoglobulin-secreting plasma cells. "Moreover, immunohistochemical profiling revealed distinct expression patterns—such as elevated PD1 and CD56, and altered BCL6 expression—in clonal cases, which may serve as useful biomarkers for early recognition of plasma cell neoplasm transformation in AITL patients." (PMID 41357603, 2025).
sarcopenia (3 papers, 2024 to 2025). Progressive decline in muscle mass due to aging which results in decreased functional capacity of muscles. "Correspondingly, the sarcopenia model showed marked differential expressions of BCL6, DDIT4, FLNA, FOXO1, NFKBIA, PGK1, and STAT3." (PMID 41282482, 2025). "A bioinformatics study identified BCL6 as a key hub gene linking knee OA and sarcopenia." (PMID 39640258, 2024).
squamous cell carcinoma (3 papers, 2020). A carcinoma arising from squamous epithelial cells. "Moreover, a comparison to previous transcriptome data of BCL6 in epidermoid carcinoma cells reveals that BCL6 targets the same genes in trophoblastic cells and malignant cells, likely to modulate cell invasion." (PMID 33182312, 2020). "Indeed, the genes ACTG1, CAV1, MYLK, and PAK were also found to be deregulated in a transcriptomic analysis of epidermoid carcinoma cells A431, indicating that BCL6 modulates the invasion capacity of physiological and malignant components through similar molecular mechanisms." (PMID 33182312, 2020).